ABCG2 (ATP binding cassette subfamily G member 2 (JR blood group))
Diseases named in the same sentence as ABCG2 in open-access papers (continued):
Sharing a sentence is not in itself a finding about the gene and the disease.
cancer (continued). "This phenomenon is witnessed in tumors overexpressing ABC family of transporters such as P-gp, MRP1/ABCC1 and BCRP/ABCG2 and is one of the promising procedures to treat drug resistant cancer cells." (PMID 32742605, 2020). "Increasing evidence suggests a crucial role of ABCG2 in intrinsic MDR of cancer stem cells, a small cell population in cancers, sharing several characteristics of normal stem cells." (PMID 33066132, 2020). "ABCG2 promoter demethylation, accompanied by overexpression of ABCG2, has been detected after treating CCRF-CEM with the anti-cancer drug sulfasalazine." (PMID 33066132, 2020). "ABCG2 is one of the promising markers for CSCs identification and is known to contribute to multidrug resistance (MDR) in cancer chemotherapy." (PMID 32397297, 2020). "An MTT assay showed that ABCG2 overexpression significantly desensitized both the cancer cells and ABCG2 transfected-HEK293 cells to tivantinib and that this drug resistance can be reversed by ABCG2 inhibitors." (PMID 31940916, 2020). "Only in a few cancers is the expression of ABCB1 and/or ABCG2 proteins higher than that found in normal tissues." (PMID 31729540, 2020). "BCRP (ABCG2) is a 72 kDa half-transporter that acts as a homomeric dimer, and so far, BCRP is known to mediate resistance to a variety of anti-cancer agents, among these the chemotherapeutic agents SN-38, topotecan, mitoxantrone, doxorubicin, and daunorubicin." (PMID 32143347, 2020). "Breast cancer resistance protein (BCRP/ABCG2), an ATP-binding cassette (ABC) efflux transporter, plays a critical role in multi-drug resistance (MDR) to anti-cancer drugs and drug–drug interactions." (PMID 33430990, 2020). "ABCG2 is an ABC transporter that extrudes a variety of compounds from cells, and presents an obstacle in treating chemotherapy-resistant cancers." (PMID 32385283, 2020). "It has been suggested that topotecan resistance in some types of cancers is related to the overexpression and active drug efflux functions of ABCB1 and ABCG2." (PMID 33425914, 2020). "Regarding the drug transporter regulation, it is known that efflux transporters ABCG2 (BCRP) and ABCB1 (P-gp) are induced by TCDD mediated AhR activation in Caco-2 and other human carcinoma cells including HepG2, LS180, LS174T and MCF7 cells." (PMID 33551819, 2020). "In the present study, we revealed an additional action of TMP195 on resensitizing ABCB1- and ABCG2-overexpressing multidrug-resistant cancer cells to multiple therapeutic drug substrates of ABCB1 and ABCG2." (PMID 31905792, 2019). "It is worth noting that Apatinib also reverses the multidrug resistance (MDR) condition in several cancer cell lines by the inhibition of ATP Binding Cassette Subfamily B Member 1 (ABCB1) and ATP-binding cassette superfamily G member 2 (ABCG2)." (PMID 31570733, 2019). "We found that TMP195 reversed ABCG2-mediated resistance to mitoxantrone and topotecan to a comparable level as that of Ko143, an ABCG2 benchmark inhibitor, in S1-M1-80 and H460-MX20 cancer cells." (PMID 31905792, 2019). "ABCG2 is considered to be a potential biomarker for CSCs in ESCC, and ABCG2-positive cancer seemed to produce more stemness." (PMID 30979011, 2019). "In RGK36 and RGK45 cells, HCP-1 expressions were increased, while the expressions of ATP-binding cassette sub-family G member 2 (ABCG2), which exports porphyrins and some anti-cancer drugs from cells, were decreased by the hyperthermia treatment." (PMID 30733583, 2019). "Overexpression of ATP-binding cassette (ABC) transporters, such as ABCB1 and ABCG2, has been proved to be a major trigger for multidrug resistance (MDR) in certain types of cancer." (PMID 31472682, 2019). "Next, we examined the effect of TMP195 on apoptosis induced by ABCB1 substrate drug colchicine and by ABCG2 substrate drug topotecan, known inducers of apoptosis, in ABCB1- and ABCG2-overexpressing human cancer cell lines." (PMID 31905792, 2019).
cancer (continued). "These sphere-dispersed (sphere cells) cells had elevated mRNA levels of important cancer stem cell (CSC) makers including CD44, CD133, ALDH, ABCG2, OCT4, and Nanog compared with their parental cells in both OC-3-IV and C9-IV3 sublines." (PMID 30782177, 2019). "To this end, we explored the potential mechanism and chemosensitizing effect of TMP195 in multidrug-resistant cancer cells overexpressing ABCB1, ABCC1 or ABCG2." (PMID 31905792, 2019). "Efflux transporters (e.g., P-gp/ABCB1, ABCC1, and ABCG2) and influx transporters (e.g., SLC22A16) are involved in Dox resistance in cancer cells." (PMID 31293428, 2019). "In cancer cells, as with other ABC transporters, ABCG2 is highly expressed, resulting in reduced drug concentrations inside the cell and consequent drug resistance." (PMID 35582590, 2019). "The ATP-binding cassette transporter G2 (ABCG2; also known as breast cancer resistance protein, BCRP) has been suggested to be involved in clinical multidrug resistance (MDR) in cancer like other ABC transporters such as ABCB1 (P-glycoprotein)." (PMID 30890942, 2019). "We confirmed that TMP195 reversed ABCB1- and ABCG2-mediated drug resistance by enhancing drug-induced apoptosis in ABCB1- and ABCG2-overexpressing multidrug-resistant cancer cells." (PMID 31905792, 2019). "The correlation coefficient between the expression level of cancer stem cell markers ALDH1A1, CD44, OCT3/4, and ABCG2 with the stages of PTC tumors as well as TFA samples was calculated." (PMID 31341476, 2019). "A recent paper implicated the role of aberrantly methylated miR-212-3p and miR-132-3p in ccRCC in the post-transcriptional regulation of BCRP/ABCG2 (breast cancer resistance protein), which contributes to the multi-drug resistance seen in cancer." (PMID 31110513, 2019). "SAB reversed the multi drug resistance in colon CSCs (cancer stem cells) xenografted mouse model via reduction of SOX2, CD44 and ABCG2 expression." (PMID 31592132, 2019). "The cytotoxicity assay indicated that the IC50 values of olmutinib for ABCB1-, ABCG2-, and ABCC1-overexpressing cancer cells (KB-C2, NCI-H460/MX20 and KB-CV60) were 11.42, 12.19, and 17.14 μM." (PMID 30356705, 2018). "α-Mangostin, a natural xanthone derived from Garcinia mangostana L, selectively inhibited ABCG2-mediated drug transport and reversed MDR in ABCG2-overexpressing MDR cancer cells." (PMID 29749405, 2018). "We have chosen three ABC-transporters, i.e., P-glycoprotein (MDR1/ABCB1) and breast cancer resistance protein (BCRP/ABCG2) as well-known MDR-mechanisms and ABCB5 as novel efflux transporter relevant for cancer stem-like cells." (PMID 29707146, 2018). "These cancer stem cell markers, including CD24, CD44, CD117, CD133, ALDH, ABCG2, OCT4, and Nanog, were significantly higher in Hep3B sphere cells shown by qRT–PCR analysis." (PMID 29848298, 2018). "Cancer cells acquire MDR via various types of ABC transporters; for example NSCLC cells obtain MDR due to overexpression of ABCG2." (PMID 30356705, 2018). "Stem cell markers CD133, CD44, ABCG2, Oct4, Lgr5, and CD24 are also highly expressed in cancer stem cells." (PMID 29422082, 2018). "Our results indicated that the incubation of the ABCG2 overexpressing cancer cells, H460-MX20, with 10 or 20 μM cariprazine for 24 h significantly decreased ABCG2 protein levels in in a concentration dependent-manner." (PMID 30181510, 2018). "There are at least three ABC transporter genes involved in cancer drug resistance—P-glyocoprotein/MDR1 (ABCB1), MRP2 (ABCC2), and BCRP (ABCG2)—which have distinct, but overlapping, spectra of substrates." (PMID 29732370, 2018).
cancer (continued). "The commonly reported specific surface markers, such as CD44, CD133, OCT-4, Bmi-1, ALDH1, ABCG2 and KLF4, with high expressions, are usually used to isolate cancer stem cells from cell lines." (PMID 29559853, 2018). "qPCR analysis showed increased expression of many CSC marker genes such as ALDH1, ABCG2, NESTIN, EpCam and CD90, altogether suggesting that hTERT plays a significant role in the expression of cancer and CSC markers." (PMID 29907642, 2018). "Inhibition of ABCG2 is a logical approach to overcome MDR and it is considered clinically significant in cancer chemotherapy." (PMID 29458405, 2018). "We also tested the effect of AF and its combination with ADM on the expression of cancer stem cell markers including SOX2, Oct4, and ABCG2." (PMID 29367724, 2018). "These cancer stem-like cells express important hepatic CSC markers such as CD24, CD44, CD117, CD133, ALDH, ABCG2, Oct4, and Nanog which were extensively reported before." (PMID 29848298, 2018). "Many studies have used putative cancer stem cell markers, such as CD133, CD44, ABCG2, and side population via Hoechst efflux assay, to isolate and enrich for cells capable of forming tumors [tumor-initiating cells (TIC)]." (PMID 28388544, 2017). "Thus, the development of small molecules targeting these specific motifs may become a promising alternative to develop novel and specific ABCG2 efflux modulators able to tackle MDR in cancer by impairing drug-induced signal transmission, similar to what was recently suggested for P-gp66." (PMID 29138424, 2017). "Among DRP protein members, ABCG2, P-gp and MDR-1 over-expression has been reported in many cancers and drug resistance cells." (PMID 29137307, 2017). "ABC proteins responsible for multidrug resistance in human cancers include the multidrug resistance protein 1 (MRP1/ABCC1), P-glycoprotein (P-gp/ABCB1), and the breast cancer resistance protein (BCRP/ABCG2)." (PMID 28409029, 2017). "It is well established that the overexpression of p-glycoprotein (P-gp or ABCB1) and breast cancer resistance protein (BCRP or ABCG2) play a major role in mediating MDR in certain types of cancer cells." (PMID 28824426, 2017). "We also studied whether ABCB1 (P-glycoprotein) and ABCG2 (BCRP, breast cancer resistance protein), which are usually considered the main drug transporters underlying the multidrug resistance (MDR) phenotype in cancer cells, compromise the antiproliferative effects of EF-24 in K562 cells." (PMID 29088066, 2017). "The major ABC superfamily transporters associated with multidrug resistance development were ABCB1, MRP2/ABCC2, and BCRP/ABCG2, which were often enriched with cells cancer stem cell-like phenotypes." (PMID 28903328, 2017). "ABCG2, together with ABCB1, is one of the major efflux transporters of TKIs and is strongly expressed in drug-resistant cancer cells." (PMID 29190894, 2017). "qPCR analysis showed increased expression of many cancer stem cell marker genes such as ALDH1, ABCG2, CD90, NESTIN, PTEN, and EpCam." (PMID 29115987, 2017). "In primary cancer tissues ABCB1 and ABCG2 expression levels were different in the two NSCLC subtypes." (PMID 28340578, 2017). "Accordingly, we next looked at a potential relationship between 14q32 miRNAs expression and cancer stem cell markers, and we examined the expression of CD44, ABCG2, ALDH1A1, NANOG and c-MYC genes in 53 tumor samples." (PMID 27980227, 2017). "In particular, ABCG2 has been shown in various tumors to be upregulated in the side population TIC and, in some tumors, is considered to be an additional cancer stem cell marker." (PMID 28388544, 2017). "In several cancer entities, aberrant ABCB1 or ABCG2 methylation was shown, i.e. in leukemia or solid tumors and was also observed in drug-resistance." (PMID 29190894, 2017). "PITX2 and β-catenin pathways upregulate the ABC transporter system, especially ABCG2, which is also known as BCRP (breast cancer resistant protein)." (PMID 29138528, 2017).
cancer (continued). "Among them, P-glycoprotein (P-gp/ABCB1), multidrug-resistant protein 1 (MRP1/ABCC1), breast cancer resistant protein (BCRP/ABCG2/MXR/ABCP), and multidrug-resistant protein 10 (ABCC10/MRP7) transporters frequently drive chemosensitive cancers to MDR." (PMID 28646911, 2017). "In cancer cell lines with (weak) expression of ABCG2 (DMS114, A549, HCC827 and MCF-7), the mean promoter methylation status of ABCG2 was in the range from 5 to 32%." (PMID 27689338, 2016). "The expression levels of the cancer stem cell‐specific markers CD44, CD133, and ABCG2, the tumor suppressor genes p21 and p16, and the endoplasmic reticulum (ER) stress‐related genes IRE1, GRP78/BIP, and ARTC were determined by quantitative PCR." (PMID 27239442, 2016). "Side population cell sorting technology is widely used to identify cancer stem cell-like cells in cancer, and the ABC transporter family member ABCG2 is an unfavorable prognostic factor in ESCC." (PMID 27189061, 2016). "Moreover, the in vivo inhibition of ABCG2 could also be useful in cancer therapy." (PMID 28082903, 2016). "The 19 human cancer cell lines investigated in the present study were found to differ in the methylation status of the ABCB1 and ABCG2 promoter." (PMID 27689338, 2016). "Expression of ABCG2, a drug resistance gene, in ALDH-positive cells has been observed in normal stem cells, cancer stem cells, and drug resistant cancers." (PMID 26654944, 2016). "In dormant cancer cells, transporter expressions of PEPT1, ALA importer, and ABCB6, an intermediate porphyrin transporter, were upregulated and that of ABCG2, a PpIX exporter, was downregulated." (PMID 27857072, 2016). "Thereby, ligand-activation of GPER generates a feedforward loop coupling IL1β induction by CAFs to IL1R1 expression by cancer cells, promoting the up-regulation of IL1β/IL1R1 target genes such as PTGES, COX2, RAGE and ABCG2." (PMID 27072893, 2016). "SALL4 characterizes a feature of drug resistance through the maintenance of side population cancer stem cells and affects the side population cells by regulation of ABC drug transport genes ABCG2 and ABCA3 in leukemic cells." (PMID 26935744, 2016). "The overexpression of ATP-binding cassette (ABC) transporters, particularly ABCB1, ABCC1 and ABCG2, play a key role in mediating MDR by pumping anticancer drugs out from cancer cells." (PMID 26556876, 2015). "Preliminary data had suggested tozasertib also to be a substrate of the ABC transporter ABCG2, another ABC transporter potentially involved in cancer cell drug resistance." (PMID 26415506, 2015). "In the TOP-GFPHigh fraction, the invasion abilities, the sphere-forming ability, the SP percentage and the expression level of ABCG2 were much higher than those of the TOP-GFPLow fraction in many cancer cell lines." (PMID 26075748, 2015). "ABCG2 and ERCC1 can both serve as chemoresistance markers for most types of cancer, and in the present study, we measured the IC50 values of DDP and the expression levels of ABCG2/ERCC1 to investigate DDP resistance in TSCC cells." (PMID 26517090, 2015). "The SP fraction has an enhanced ability to efflux small molecules, including anti-cancer agents, and this efflux activity is regulated by ABC transporters such as ABCB1 and ABCG2 (refs 15, 16)." (PMID 26065921, 2015). "RT-PCR analysis further revealed that cancer cells upregulate several CSC markers upon co-culture with ADSCs, including SOX2, NANOG, ALDH1A1, and ABCG2." (PMID 25797257, 2015). "Extensive studies have linked 3 ABC-superfamily multidrug efflux pumps, namely ABCB1/MDR1, ABCC1/MRP1, and ABCG2/BCRP, to cancer cell drug resistance." (PMID 26305906, 2015). "Tozasertib was suggested to also interfere with ABCG2 (also known as BCRP), another ATP-binding cassette (ABC) transporter known to be involved in cancer cell drug resistance, but conclusive experimental evidence has been missing." (PMID 26415506, 2015).
cancer (continued). "Enzastaurin has been reported to display enhanced activity in combination with various anti-cancer drugs [see e.g. 11, 13, 17, 19, 41; 58–60] including ABCB1, ABCG2, and/or ABCC1 substrates such as paclitaxel, docetaxel, erlotinib, and doxorubicin." (PMID 25749379, 2015). "Significant changes in tumor angiogenesis, cancer cell proliferation, apoptosis, HIF1α levels, HIF-1 target genes and ABCG2 were found both in vitro and in tumor tissue." (PMID 26623560, 2015). "Overexpressing the adenine triphosphate (ATP)-binding cassette (ABC) transporters, particularly ABCB1 (MDR1/P-glycoprotein), ABCC1 (MRP1) and ABCG2 (BCRP), are one of most common reasons to result in MDR in cancer cells." (PMID 25915534, 2015). "Here, it is our intention to review: 1) recent discoveries that further characterize the role of ABCG2 in oncology, and 2) advances in reversing and circumventing ABC transporter-mediated resistance to anti-cancer therapies." (PMID 26714461, 2015). "Moreover, ABCG2 expression may be involved in cancer cell drug resistance." (PMID 26415506, 2015). "The ability to efflux Hoechst dye via the multidrug resistance transporter ATP-binding cassette sub-family G member 2 (ABCG2) as identified by side population (SP) has proven to be a valuable marker for CSCs from various solid tumors and cancer cell lines." (PMID 24939878, 2014). "During the process of studying its anti-cancer properties, curcumin was found to inhibit ATP-binding cassette (ABC) family members including ABCA1, ABCB1, ABCC1, and ABCG2." (PMID 24653706, 2014). "Other described targets include ABCG2 (breast cancer-resistance protein, BRCP1) and ABCB1 (P-glycoprotein, MDR1), which were found to be overexpressed in doxorubicin-resistant ATC cancer cells." (PMID 24424445, 2014). "The co-culture of cancer cells and PSCs induced an alteration in expression of the CSC-related genes: nestin, ABCG2 and LIN28 in the cancer cells, indicating a CSC-like phenotype." (PMID 25337831, 2014). "In contrast, protein expression of ATP7b (copper transporter ATP7b), mRNA expression of ABCG2 (BCRP, breast cancer resistance protein), ABCC2 (MRP2), and SLC31A1 (hCTR1, human copper transporter 1) did not correlate with survival." (PMID 25275603, 2014). "In consequence, it is comprehensible that patients with high expression of ABCG2 and ABCC2 (and thus potentially high cancer-stem cell burden) exhibit poor survival." (PMID 25275603, 2014). "ABCG2 is responsible for the multidrug resistance (MDR) phenotype, and strongly modulates cancer outcomes." (PMID 25474134, 2014). "The breast cancer resistance protein (BCRP, also called ABCG2) produces MDR in a broad range of human cancers." (PMID 24626598, 2014). "Several miRNAs have been found to regulate drug resistance genes such as ABCG2 and MDR1 and the modulation of miRNAs expression or function has been reported to alter the sensitivity of cancer cells to anticancer drugs." (PMID 24786846, 2014). "Regarding the regulation of cancer chemoresistance, there are some reports that CD147 regulates certain proteins, e.g., ATP-binding cassette transporter G2 (ABCG2) and EGFR, to mediate chemoresistance." (PMID 25268615, 2014). "BCRP/ABCG2 and MDR1 are two major regulators controlling the brain distribution of anti-cancer drugs." (PMID 24391798, 2013). "Three ABC transporters, including P-glycoprotein (P-gp, MDR1, ABCB1), multidrug resistance protein 1 (MRP1, ABCC1), and breast cancer resistance protein (BCRP, MXR, ABCG2), play important roles in most cases of MDR in cancer cells." (PMID 24391798, 2013). "For example, human ABCG2 (BCRP/MXR/ABCP), a protein involved in multidrug resistance in cancer cells, is responsible for enhanced exposure of PS at the plasma membrane of ABCG2 overexpressing cells due to increased outward PS transport." (PMID 23638200, 2013). "MCSCs possessed the high expression of cancer stem cell markers (CD133, CD44, OCT4, NANOG, and ABCG2) and the ability of differentiation." (PMID 24188098, 2013).